MIR1263 (microRNA 1263)
Synonyms: hsa-mir-1263; MIRN1263
Gene: MicroRNA gene on chromosome 3 (164,171,471 to 164,171,556, reverse strand). Ensembl gene ENSG00000221251.
Diseases named in the same sentence as MIR1263 in open-access papers:
MIR1263 is named in the same sentence as 1 disease in open-access papers, as found by Europe PMC text mining. Sharing a sentence is not in itself a finding about the gene and the disease. The quoted sentences say what the papers report.
cancer (1 paper, 2023). A tumor composed of atypical neoplastic, often pleomorphic cells that invade other tissues. "Among which three genes, EXOC6 (Padj|ESCC=7.30×10-3, Padj|GC=6.00×10-4, Padj|CRC=2.6×10-2), LRP5L (Padj|ESCC=2.70×10-3, Padj|GC=5.70×10-3, Padj|CRC=1.65×10-2), MIR1263/LINC01324(Padj|ESCC=3.22×10-2, Padj|GC=4.36×10-2, Padj|CRC=3.26×10-2) were statistically significant in all three cancer types." (PMID 37483484, 2023).